CTLA4 (cytotoxic T-lymphocyte associated protein 4)
Diseases named in the same sentence as CTLA4 in open-access papers (continued):
Sharing a sentence is not in itself a finding about the gene and the disease.
melanoma (continued). "Immune checkpoint inhibitors targeting CTLA-4, PD-1, and PD-L1 have shown clinical benefit for patients with non-small cell lung cancer (NSCLC), advanced melanoma and several other cancers." (PMID 31234517, 2019). "Demonstration of preclinical efficacy of CTLA‐4 antibodies prompted clinical trials, with a phase‐III trial observing improvement in overall survival for patients with advanced melanoma." (PMID 31485330, 2019). "Ipilimumab, CTLA-4 inhibitor, the first immune checkpoint inhibitor approved by FDA, was used to treat patients with advanced melanoma and has demonstrated improved survival when given with gp100 melanoma vaccine." (PMID 31181772, 2019). "Based on the impressive preclinical data in melanoma model, several IDO inhibitors are explored in combination with CTLA-4 and PD-1 inhibition." (PMID 30853982, 2019). "In the present study, we treated established tumors with melanoma-specific adoptive CD4+ T cell transfer and costimulation via OX40 or CTLA-4 blockade." (PMID 30400822, 2018). "In addition, in TCGA patients with melanoma, reduced levels of ESRP1 (which encodes a master splicing regulator involved in EMT) were correlated with increased immune checkpoint expression (PD-L1 and CTLA4) and elevated tumor-associated immune cytolytic activity." (PMID 30240750, 2018). "Preclinical experiments in murine melanoma model indicated a durable response with additional radiofrequent ablation (RFA) and CTLA-4 blockade by enhancing antigen presentation within the tumor area." (PMID 30400835, 2018). "Summary of clinical features from independent group of 10 melanoma patients treated with anti-CTLA-4 (n = 3), anti-PD-1 (n = 3), or combined anti-CTLA-4/anti-PD-1 (n = 4), and from whom serum samples were used to assess assay reproducibility." (PMID 29606147, 2018). "Despite advancements in targeted therapies (BRAF inhibitors) or immunotherapies (anti-CTLA-4 or anti-PD1), most patients with melanoma will need additional treatment." (PMID 29743521, 2018). "DC vaccination successfully increased the frequency of functional melanoma-specific CD8 and CD4 T cells, and approximately 7–10% of tumour-specific CD8 cells were CTLA-4 positive while 20–28% were PD-1 positive." (PMID 29996914, 2018). "Antibodies targeting CTLA4, PD1, and programmed death 1 ligand (PDL1) have demonstrated significant efficacy in non-small-cell lung cancer, renal cancer, and melanoma." (PMID 29868007, 2018). "From the melanoma experience, PD-1+/CD8+ TILs are known to express CTLA4 and Ki67 markers and lack expression of CD127, a phenotypic characteristic of exhausted T-cells." (PMID 29910795, 2018). "Subgroup analyses by type of cancer (melanoma vs. NSCLC) and type of ICI (CTLA-4 inhibitors vs. PD-1 inhibitors) were also performed." (PMID 30545122, 2018). "The clonal neoantigen load was correlated with OS in lung adenocarcinoma (LUAD), and the sensitivity to PD-1 and CTLA-4 blockade in patients with NSCLC and melanoma was enhanced in tumors enriched in clonal neoantigen." (PMID 30060457, 2018). "A recent study showed that H3K27me3 inhibition combined with CTLA-4 blockade results in greater tumor remission and Treg reduction than CTLA-4 blockade therapy alone in melanoma-bearing mice." (PMID 29735917, 2018). "For example, transcriptome analysis of tumor biopsies from 40 melanoma patients before treatment with anti-CTLA-4 indicated higher expression of the CYT score, CTLA-4, PD-1, PD-L1, and PD-L2 in patients with clinical benefit." (PMID 29968076, 2018). "Unprecedented responses have been seen among patients with advanced cancers including melanoma, lung, bladder, RCC and Hodgkin’s disease, treated with anti-CTLA-4, PD-1/L1." (PMID 28866656, 2018). "When used in combination with anti-PD-L1 and anti-CTLA-4 antibodies, cytotoxicity of TAMs and CD8+ T cells in the same melanoma model was potentiated." (PMID 30349530, 2018).
melanoma (continued). "In 2011, the FDA approved the first anti-CTLA-4 antibody, Ipilimumab (trademark name YERVOY®), for the treatment of melanoma." (PMID 29713453, 2018). "We tested this idea by assessing the therapeutic synergy of NKTR-214 with CTLA-4 and PD-1-based checkpoint blockade therapy or with peptide-vaccination in CT26 colon carcinoma and B16 melanoma models." (PMID 30400822, 2018). "We transplanted B16F10 mouse melanoma cells subcutaneously in B6 mice and treated with vehicle, anti-CTLA-4, karonudib, or combination of CTLA-4 and karonudib." (PMID 30042422, 2018). "The combined use of CTLA-4 and PD-1 checkpoint inhibitors resulted in the rejection of B16-BL6 melanoma in 50% of test animals." (PMID 29769148, 2018). "Immune checkpoint inhibitor therapy has been particularly successful in melanoma, for which approved treatments now include anti-PD-1 (nivolumab and pembrolizumab), anti-CTLA-4 (ipilimumab), and combination anti-PD-1/CTLA-4 regimens (nivolumab–ipilimumab)." (PMID 29319049, 2018). "IDO1 has also been reported to participate in a resistance mechanism to checkpoint inhibitors, and the combination of CTLA-4 blockade and an IDO1 inhibitor resulted in more effective antitumor immunity in a melanoma mouse model." (PMID 30068361, 2018). "Ezh2 inactivation reversed this resistance and synergized with anti-CTLA-4 and IL-2 immunotherapy to lead to intratumorally accumulation of IFN-γ-producing PD-1low CD8+ T cells and PD-L1 downregulation to suppress melanoma growth." (PMID 29556394, 2018). "The area on immune checkpoint blockades has witnessed rapid progression, especially the monoclonal antibodies for PD-1/PD-L1 and CTLA-4, which have been proved by FDA for melanoma and/or lung cancer as sole reagents." (PMID 27756892, 2017). "Finally, immune checkpoint blockade (ICB) with antibodies targeted to cytotoxic T lymphocyte antigen-4 (CTLA-4) (ipilimumab) and programmed cell death protein 1 (PD-1) (nivolumab and pembrolizumab) has resulted in significant improvements in clinical outcomes for a proportion of melanoma patients." (PMID 29276510, 2017). "The first immune checkpoint inhibitor to enter clinic trials was ipilimumab, an CTLA-4 blocking antibody, whose approval by the FDA was based on the results from trials in patients with advanced melanoma with an acceptable adverse event profile." (PMID 29157287, 2017). "In this context and encouragingly, the effectiveness of the combination of ACT with IL-21-primed polyclonal cytolytic T cells and anti-CTLA-4 antibody in a melanoma patient that had failed prior treatments with ACT and anti-CTLA-4 has recently been reported." (PMID 28497159, 2017). "Using B16 mouse melanoma cells we discovered that pre-treatment with AR42 or sodium valproate enhanced the anti-tumor efficacy of an anti-PD-1 antibody and of an anti-CTLA4 antibody." (PMID 29137331, 2017). "This includes the appearance of vitiligo in C57BL/6 mice bearing melanoma tumors and treated with a variety of immunotherapy strategies or the induction of hypophysitis in SJL/J mice treated with multiple treatments of CTLA-4 blockade." (PMID 28239469, 2017). "Ipilimumab, a fully human IgG1 mAb that blocks the cytotoxic T lymphocyte-antigen-4 (CTLA-4), a checkpoint inhibitor of T cell activation, was the first ICI approved, in 2011, for use in advanced melanoma." (PMID 29162153, 2017). "Both address critical and independent pathways of advanced melanoma growth: the mitogen-activated protein (MAP) kinase signaling pathway for vemurafenib and the CTLA-4 signaling pathway for ipillimumab." (PMID 29179523, 2017). "Recent work has demonstrated that combinatorial treatment with anti-CTLA-4 antibodies and low-dose AZA or DAC results in significantly decreased tumor growth of melanoma cells in a murine xenograft setting, compared with CTLA-4 therapy alone." (PMID 28359286, 2017).
melanoma (continued). "The authors also found that combination of CIS inhibition with CTLA4 and PD1 blockade had a greater effect in reducing melanoma metastasis than either of these treatments alone." (PMID 28536525, 2017). "A humanized anti-CTLA4 monoclonal antibody (ipilimumab) was approved by the Food and Drug Administration (FDA) for metastatic and advanced melanoma." (PMID 28174608, 2017). "In the B16-F10 mouse melanoma model, multiple combinations of low-dose 5-AZA directly enhanced tumor responses to anti-CTLA4 immune checkpoint therapy." (PMID 28149332, 2017). "Targeting CTLA-4 and PD-1/PD-L1 pathways via using anti-CTLA-4 and anti-PD-1/anti-PD-L1 has achieved more efficacies in regressing melanoma, as compared to other cancers such as renal cell carcinoma." (PMID 28567163, 2017). "The current immunotherapy for melanoma include cytokine agents (IL-2 and IFN-α) and antibodies against CTLA-4 and PD-1." (PMID 28567163, 2017). "The melanoma immunotherapies include the cytokine therapies consisting of IFN-α and IL-2 and inhibitors to CTLA-4 (ipilimumab) and PD-1 (nivolumab, lambrolizumab and pembrolizumab)." (PMID 28567163, 2017). "Melanoma was the first malignancy in which checkpoint inhibitory immunotherapy antibodies were approved, blocking the actions of PD1/PD-L1 and CTLA4." (PMID 29137331, 2017). "In mouse melanoma models, IDO is an essential mechanism of resistance to ICKB, including CTLA-4 and PD-1." (PMID 28970830, 2017). "The human mAb, ipilimumab, inhibits Tregs by blocking CTLA-4 and is FDA approved for use in melanoma patients." (PMID 28855899, 2017). "In particular, in a melanoma mouse model administration of commensal probiotics has shown to improve tumor control alone and in association with PD-L1 blockade; on the other hand tumors in antibiotic-treated or germ-free mice did not respond to CTLA-4 blockade." (PMID 28919861, 2017). "Preclinically, combination therapy with epacadostat and anti-CTLA-4 or anti-PD-1/PD-L1 improved tumor control and increased IL-2 production and CD8 T-cell proliferation in murine melanoma better than single agent therapy." (PMID 27192116, 2016). "Ipilimumab is an antibody able to block the co-inhibitory receptor cytotoxic T-lymphocyte antigen-4 (CTLA-4) and the inhibition of CTLA-4 contributes to a global activation of the immune system and thereby improving the survival status of melanoma patients." (PMID 27764796, 2016). "Despite the spectacular achievements of targeted therapies (BRAF inhibitors) or immuno-therapies (anti-CTLA4 or anti-PD1), most patients with melanoma will need additional treatments." (PMID 27756874, 2016). "With routine use of combination and sequential anti-CTLA-4 and anti-PD1 therapy in melanoma patients, this clinical scenario will likely be encountered with more frequency and providers will be challenged to decide on appropriate anti-melanoma therapy." (PMID 28031822, 2016). "An alternative mechanism of action of some ICBs would be to directly deplete cells expressing these markers, as observed with the anti-CTLA-4 ipilumimab, which induces direct elimination of CTLA-4+ regulatory T cells in tumor tissue in patients with melanoma." (PMID 27415008, 2016). "Ipilimumab, an antibody that blocks CTLA-4, was approved by the U.S. Food and Drug Administration (FDA) for patients with advanced melanoma in 2011." (PMID 26788324, 2016). "The combination of both anti-CTLA-4 and anti-PD1 has been shown to be twice as effective as either treatment alone in the rejection of B16-F10 melanoma tumors." (PMID 27917371, 2016). "Since that time, two humanized anti-CTLA-4 mAbs, ipilimumab (IgG1) and tremelimumab (IgG2), have been developed and evaluated in phase III trials in advanced melanoma." (PMID 31093342, 2016). "Ipilimumab, an anti-CTLA-4 antibody, was approved by the FDA in 2011 as a first-line therapy for melanoma patients with metastatic disease, based on phase III trials that showed prolongation of overall survival." (PMID 27151159, 2016).
melanoma (continued). "Currently, T-VEC combined with anti-CTLA-4 (ipilimumab) is studied in a phase II trial (NCT01740297) and combined with anti-PD-1 (pembrolizumab) in a phase Ib/III trail (NCT02263508), both in melanoma patients." (PMID 27847783, 2016). "Immune-checkpoint blocking antibodies including anti-CTLA-4 and anti-PD1 can induce tumor responses in various tumor types including melanoma, non-small cell lung cancer (NSCLC), renal cell cancer (RCC), and Hodgkin disease." (PMID 27532025, 2016). "It has been demonstrated that sensitivity to PD-1 and CTLA-4 blockade in patients with advanced NSCLC and melanoma was enhanced in tumors enriched for clonal neoantigens." (PMID 27650038, 2016). "Co-expression of CTLA-4 and PD-1 has been detected in HCV-specific T cells as well as in melanoma TIL." (PMID 27610613, 2016). "In fact, in melanomas, hotspot regions or amplification of KIT, PIK3CA, MITF and CTLA4 are often analyzed." (PMID 26863566, 2016). "In melanoma, tumors can become established by activation of the negative regulator of cytotoxic T lymphocytes (CTLs), CTL antigen-4 (CTLA-4)." (PMID 26155423, 2015). "We therefore propose that COX-2 levels and COX-dependent inflammatory mediators in human melanoma and other cancers might constitute useful biomarkers predictive of prognosis and treatment outcome, including in response to checkpoint blockade inhibitors, such as anti-CTLA4 and anti-PD-1/PD-L1." (PMID 26343581, 2015). "In a preclinical mouse B16F10 melanoma model, combined blockade of TIM-3 and PD-1, or TIM-3 and CTLA4, was more effective in prolonging survival than blocking either protein alone." (PMID 25614821, 2015). "Two phase 1 clinical trials suggested even further improvements for melanoma patients, by combination therapies with PD1 and CTLA-4 blocking monoclonal antibodies." (PMID 26167163, 2015). "The monoclonal antibodies against cytotoxic T-lymphocyte antigen 4 (CTLA-4) and programmed cell death protein 1 (PD-1) were respectively approved by FDA in 2011 and 2014 for the treatment of patients with advanced melanoma." (PMID 26877890, 2015). "Antibodies, which block the T cell co-inhibitory receptors, CTLA-4 and PD-1, have now achieved FDA approval for melanoma and lung cancer (PD-1), and numerous other immunotherapeutics are demonstrating efficacy in clinical trials." (PMID 26442210, 2015). "Recently there have been a number of reports of activity of CTLA4, PD1 and PDL1 inhibitors which block tumour-induced immune suppression, particularly in melanoma but also in other malignancies including ovarian carcinoma." (PMID 24995129, 2014). "In another clinical study with melanoma patients, the combination of IFN with tremelimumab (an antibody against CTLA4) induced an increase in Treg percentage." (PMID 24608924, 2014). "In murine models of B16 melanoma tumors and CT26 colon and ID8-VEGF ovarian carcinomas, dual blockade of CTLA-4 and PD-1 enhanced greater tumor rejection than each alone." (PMID 24904570, 2014). "To test this notion, we utilized permutations of anti-CTLA-4 mAb, anti-PD-L1 mAb, and/or the IDO inhibitor INCB23843 in the murine B16.SIY melanoma model." (PMID 24829760, 2014). "Ipilimumab, a human monoclonal antibody that blocks CTLA-4, has been approved by the FDA for first line treatment of advanced melanoma." (PMID 25013914, 2014). "Recent work has shown that blockade of regulatory T cell function with CTLA4-blocking antibodies has revealed impressive “repressed” CD8 immune responses to neo-antigens expressed by human cancers, particular melanoma, but also some other solid tumors." (PMID 24782861, 2014). "Anti-CTLA-4 antibodies have been used in combination with oncolytic parvovirus in vitro and Newcastle disease virus (NDV) in vivo to treat murine B16 melanoma." (PMID 25101247, 2014). "Blocking PD-1 in vivo in a mouse model for melanoma tumors resulted in improved CTL responses, although tumor growth was reduced when compared to the anti-CTLA-4 mono-therapy." (PMID 23533456, 2013).
melanoma (continued). "In a recent study, mutant BRAF-selective inhibitor and anti-CTLA-4 mAb were used in combination to treat transgenic mice with mutant BRAF and PTEN deletion that spontaneously developed melanoma." (PMID 23755373, 2013). "CTLA-4 protein expression was also found on FFPE tissue sections from 5 metastatic lesions (ML) used to originate the cell lines, and from additional melanoma lesions." (PMID 23634660, 2013). "Immunotherapy with monoclonal antibodies to block the T cell co-inhibitory molecules CTLA4, PD1, PDL1, or the combination of CTLA4 and PD1 showed clear clinical successes in the treatment of advanced melanoma." (PMID 24265631, 2013). "Immunosuppressive molecule CD200 and immune checkpoint proteins such as CTLA-4, PD-1 and CD40 expressed on melanoma cells have also been identified as possible immunotherapy candidates." (PMID 24015299, 2013). "The most prominent example here is ipilimumab, a monoclonal antibody against cytotoxic T-lymphocyte protein 4, CTLA4, and which was recently approved for the treatment of late stage melanoma." (PMID 25562700, 2012). "An anti-CTLA-4 monoclonal antibody (ipilimumab) and a BRAF inhibitor (vemurafenib) were approved in 2011 by FDA to treat advanced melanoma, which herald a new era of targeted therapeutics for melanoma." (PMID 23166634, 2012). "While both co-stimulatory modulating antibodies depressed the fraction of Tregs in B16 melanoma TIL, CTLA-4 blockade increased absolute numbers of Tregs in the tumor at day 14, whereas α4-1BB did not." (PMID 21559358, 2011). "And in recent years, for both melanoma and RCC there have been new systemic agents developed that provide clinical benefit, including the anti-CTLA-4 antibody, ipilimumab, and multi-targeted agents such as sunitinib and sorafenib." (PMID 21477295, 2011). "In melanoma, this exhaustion phenotype is enriched in tumour-reactive CD4+ and CD8+ αβ T cells which demonstrate increased expression of checkpoints including PD-1, CTLA-4, TIGIT, LAG3, TIM3, and CD39." (PMID 41325134, 2025). "Adjuvant anti-PD-1 therapy (nivolumab or pembrolizumab) has demonstrated a significant recurrence-free survival benefit over both ipilimumab (CTLA-4 inhibitor) and placebo in resected stage III–IV melanoma across multiple prospective, randomised phase III trials." (PMID 41295253, 2025). "Murine models of melanoma generated using IL-36γ overexpressing B16 cells displayed increased IFN-γ production and proliferation of CD8+ and CD4+ T cells following treatment with CTLA-4 monoclonal antibodies, compared to CTLA-4 or IL-36γ treatment alone." (PMID 40057603, 2025). "Among a cohort of patients with advanced melanoma undergoing anti‐CTLA4 and anti‐PD1 therapy, the nonresponsive subgroup showed notable SETD4 upregulation." (PMID 39817582, 2025). "Melanoma experienced the most significant rise, particularly after the 2011 FDA approval of ipilimumab following the MDX‐010‐20 trial, which demonstrated survival benefits with CTLA‐4 blockade." (PMID 39806540, 2025). "Furthermore, triple combination therapy, which includes the CSC-DC vaccine and PD1 and CTLA-4 blockade, has been shown to enhance the T-cell response against CSCs and reduce TGF-β secretion in melanoma mouse models." (PMID 40647402, 2025). "Mice bearing IFNGR1KO melanoma tumors do not respond to anti-CTLA-4 therapy, indicating that impairment of the IFN-γ signaling pathway is associated with primary resistance to CTLA-4 inhibition." (PMID 40108693, 2025). "A phase III study, the CheckMate-067 trial, investigated the efficacy of the PD-1 inhibitor nivolumab with the CTLA-4 inhibitor ipilimumab compared to monotherapies in patients with advanced melanoma who had not received treatment." (PMID 40004731, 2025).